TNF (tumor necrosis factor)
Diseases named in the same sentence as TNF in open-access papers (continued):
Sharing a sentence is not in itself a finding about the gene and the disease.
Dyskinesia (continued). "With some exceptions there is an association between the current presence of orofacial dyskinesia and TNF-α levels in the rat striatum, but now the severity of dyskinesia does not correlate with the striatal level of this cytokine." (PMID 37810262, 2023). "A study has revealed that elevated levels of IL-6 and TNF-α in Parkinson’s disease (PD) patients, along with alterations in visfatin and progranulin levels between PD patients with and without dyskinesia, indicate significant changes in inflammatory biomarkers and adipokines in PD." (PMID 40464816, 2025). "The aim of this study was to compare the levels of certain analytes, including IL-6, TNF-α, CRP, visfatin, progranulin, and 25(OH)-vitamin D, across three distinct groups, namely PD patients without dyskinesia, PD patients with dyskinesia, and healthy controls." (PMID 38392998, 2024).
focal segmental glomerulosclerosis (12 papers, 2016 to 2024). A renal disorder characterized by sclerotic lesions in the glomeruli. "Finally, we demonstrate that organoids react to TNFα with a global inflammatory response similar to the molecular changes associated with poor outcomes for individuals with proteinuric kidney diseases focal segmental glomerulosclerosis (FSGS) or minimal change disease (MCD)." (PMID 37580326, 2023). "Microphotographs of renal tissue revealed focal segmental glomerulosclerosis and intense tubular immunopositivity for IL-6 and TNF-α after 6 months of sustained cola drinking." (PMID 27340342, 2016). "Non-proliferative GN such as minimal change disease and focal segmental glomerulosclerosis (FSGS) is primarily caused by a podocyte damage due to other cytokines including TNF-related activation-induced cytokine and unknown circulating factors finally, leading to nephrotic syndrome." (PMID 35628570, 2022). "However, cases of AKI, focal segmental glomerulosclerosis (FSGS) or IgA nephropathy have been reported in AS, RA, or inflammatory Bowel Disease patients treated with anti-TNF-α drugs." (PMID 34307414, 2021). "PCGs mainly participated in an inflammatory response, TNF-α signaling, hypoxia, epithelial-mesenchymal transition (EMT), and interferon-γ response, and was involved in focal adhesion, primary focal segmental glomerulosclerosis, PI3K-AKT signaling pathway, and AGE-RAGE pathway." (PMID 36090897, 2022). "We demonstrated that citral (3,7-dimethyl-2,6-octadienal) isolated from L. cubeba inhibited the production of nitric oxide (NO), TNF-α, and IL-6 by reducing NF-κB activation and ROS production in LPS-activated RAW264.7 macrophages and improved focal segmental glomerulosclerosis in mice." (PMID 35967819, 2022).
folate deficiency (12 papers, 2012 to 2025). A nutritional condition produced by a deficiency of FOLIC ACID in the diet. "In mice, dietary folic acid intake attenuated inflammation and fibrosis in MASH, and macrophage expression of IL-6 and TNF-α was increased with folate deficiency." (PMID 39842721, 2025). "Folate deficiency also increased IL-6, TNF-α, and MCP-1 secretions of RAW 264.7 macrophage cell line, and enhanced intestinal inflammation due to decreased colonic regulatory T (Treg) cells in mice fed a folate-deficient diet." (PMID 37630806, 2023). "Folate deficiency has been associated with impaired immune cell function and increased levels of tumor necrosis factor-alpha (TNF-α) and interleukin-6 (IL-6), which can contribute to impaired immunity, chronic inflammation, and the development of inflammatory diseases." (PMID 37960352, 2023). "Furthermore, folate deficiency is directly related to increased levels of inflammatory markers such as IL-β, IL-6, and TNF-α." (PMID 35565885, 2022). "Folate deficiency may exert pro-inflammatory signaling by enhancing the monocyte–macrophage system, and the production of the inflammatory mediators, IL1β, IL6, TNFα, and MCP1, and monocytes were significantly increased when folate deficiency." (PMID 40740648, 2025). "However, folate deficiency induced a stronger inflammatory response, as evidenced by elevated CD14 expression and increased release of CCL2 and TNFα in cells with low folate levels compared to those with normal levels." (PMID 38881906, 2024). "Both HFF diet and folate deficiency increased renal MCP-1 and IL-6 contents, as well as TNF-α." (PMID 37630806, 2023). "It has been reported that folate deficiency might enhance the expression of the inflammatory mediators including IL-1β, IL-6 and TNF-α, independent of the concentration of homocysteine." (PMID 31296192, 2019).
gonococcal infection (12 papers, 2007 to 2024). "In fact, gonorrhea leads to an extracellular inflammatory infection, which is linked to elevated levels of inflammatory cytokines and tumor necrosis factor." (PMID 39770774, 2024). "In the gonococcal infections following exposure to pathogen associated molecular patterns (PAMPs), the secretion of cytokine TNF is one of the first responses of the host immune system." (PMID 35154028, 2021). "For instance, the upregulation of TNFα, a pro-inflammatory cytokine, following Gonococcal infection in the oviduct is associated with a decrease of ciliary activities and sloughing of ciliated epithelial cells." (PMID 26542809, 2015). "PMNs can be recruited by interleukin 8 (IL8), IL6, IL1, and tumor necrosis factor-alpha (TNFα), which are produced during gonococcal infection." (PMID 38976720, 2024). "On the other hand, studies have reported that the reduction in ciliated cell activity and death of these cells during gonococcal infections has been attributed to the induction of apoptosis in FT epithelial cell by the TNF cytokine." (PMID 35154028, 2021). "Rising concentrations of TNFα during gonococcal infection correlate linearly with a decrease in ciliary activity." (PMID 30524442, 2018). "One of the first host inflammatory responses measured from gonococcal infection of fallopian tube organ cultures was the induction of tumor necrosis factor (TNF)." (PMID 30524442, 2018). "This is supported by the increased levels of TNF-α and IL-6 observed in vivo in vaginal secretions of Balb/c mice after gonococcal infection." (PMID 26125939, 2015). "In general, it is accepted that the fallopian tube tissue damage resulting from gonococcal infections can be attributed to the cytokine tumor necrosis factor alpha (TNFα)." (PMID 17257430, 2007). "In the murine infection model, P4 (1 mg/day) inhibited the inflammatory effects induced by gonococcal infections which led to decreased neutrophil infiltration, reduced polymorphonuclear neutrophils (PMNs) numbers, IL-1β, TNF-α, and IL-6 levels in vaginal secretions." (PMID 33633700, 2021). "This suggests that DC and macrophages, which are usually located in the stroma of the genital tract of the mouse, are at least in part responsible for the increased levels of TNF-α and IL-6 observed in the vaginal secretions of Balb/c mice after gonococcal infection." (PMID 24204097, 2013).
Lyme disease (12 papers, 2016 to 2025). Lyme disease (named after the towns in the USA where the disease was first identified) is a bacterial infection caused by Borrelia burgdorferi. "An example of this is in Lyme disease, caused by Lyme borreliosis, where early low TNF production is associated with worse disease outcomes." (PMID 31611882, 2019). "An increase in levels of innate and Th1-associated cytokines and chemokines, IFN-γ, IL-8, IL-6, and TNF-α has recently been reported in Lyme disease patients." (PMID 30619263, 2018). "Nevertheless, in spite of her continuation of treatment with a TNF inhibitor, the course of Lyme neuroborreliosis was smooth and the outcome one year after treatment was favourable." (PMID 31684103, 2019). "Our initial decision had been to maintain TNF inhibitor treatment in patients with EM (localized LB) but was ambiguous regarding what to do in cases of extracutaneous manifestation of LB such as Lyme neuroborreliosis." (PMID 31684103, 2019). "Inflammation in Other Chronic Conditions: Lyme disease patients are known to have increased levels of IL-1, IL-6, and TNF-α, also found in chronic fatiguing, musculoskeletal illnesses, and other neurodegenerative disorders." (PMID 30400667, 2018). "In Lyme disease, caused by Borrelia burgdorferi, which can suppress TH1 responses to persist in the host, cimetidine may enhance TH1-associated cytokines (IL-12, TNF-α, IFN-γ) and suppress TH2 cytokines (IL-10), restoring immune balance." (PMID 39937247, 2025). "This is consistent with the chronic cerebral TNF generation that maintains microglia in a chronically activated state, rather than the initial pathogen, being a plausible therapeutic target in persistent Lyme disease." (PMID 35174650, 2022). "Statistical tests turned out to be not significant for TNF-α comparisons for all groups of patients with persistent Lyme borreliosis." (PMID 31366164, 2019). "The transcript levels of several important cytokines and chemokines that have been reported to contribute to Lyme disease progression, such as IL-10, IL-1β, TNF-α, and CCL2, were upregulated in the WT- but not MT-infected tissues, which was validated by qRT-PCR." (PMID 38011206, 2023).
lymphoproliferative disorders (12 papers, 2013 to 2025). "Keeping in view the role of TNF–α in the proposed lymphomagenesis, SNP in the TNF–α promotor gene could be associated with lymphoproliferative disorders." (PMID 35886021, 2022). "It is indicated for patients who have contraindications or intolerance to the use of TNF inhibitors, a history of lymphoproliferative disorder, or after failure of at least one TNF inhibitor (third-line therapy)." (PMID 40757117, 2025). "In particular, EBV+ lymphoproliferative disorders have been seen in patients on methotrexate, tumor necrosis factor (TNF)α inhibitors, fludarabine and mycofenolate mofetil." (PMID 30899698, 2019). "Recent finding suggested that type I Cgs (detected in lymphoproliferative disorders) stimulated secretion of tumor necrosis factor-α (TNF-α) by peripheral blood mononuclear cells (PBMCs)." (PMID 24455252, 2013). "IL-1-targeted biologics have been expanding, as there are no known serious adverse effects such as lymphoproliferative disorder or virus reactivation like TNF or IL-6-targeting therapies." (PMID 31182982, 2019).
microcephaly (12 papers, 2015 to 2025). A congenital or acquired developmental disorder in which the circumference of the head is smaller than normal for the person's age and sex. "A cerebral organoid is useful to study immune responses, particularly in Zika-induced microcephaly IL-8, IL-1β, TNF-α, and IFN-γ reportedly induce intestinal inflammation caused by Entamoeba histolytica." (PMID 38900784, 2024). "Increased levels of pro-inflammatory cytokines (e.g., IL-6 and TNF-α) have been associated with an augmented risk for microcephaly in preterm newborns." (PMID 38605125, 2024). "Focusing on a specific phenotype of the CZS, the severity of the microcephaly, we found an association of it and the TNF gene." (PMID 33672623, 2021). "Children with severe microcephaly presented higher frequency of the T allele and genotypes TT or CT of the TNF rs1799724, compared with children with moderate microcephaly (p = 0.029 and p = 0.041, respectively)." (PMID 33672623, 2021). "On the other hand, the higher frequency of the TCG haplotype of TNF in individuals with moderate microcephaly, which is associated with the lower expression of TNF, could also explain this less severe phenotype in these individuals." (PMID 33672623, 2021). "Moreover, apoptosis-induced microcephaly alterations have been linked to high proinflammatory cytokines production, for instance TNFα and IL-1β." (PMID 33251156, 2020). "In this study, we reported an interesting association of alleles and haplotypes of NOS2, VEGFA, and TNF genes with the CZS development and severity of the microcephaly in the CZS." (PMID 33672623, 2021). "T allele and TT/CT genotypes of the TNF rs1799724 and haplotypes associated with higher expression of TNF were more prevalent in children with CZS and severe microcephaly (p = 0.029, p = 0.041 and p = 0.030, respectively)." (PMID 33672623, 2021). "The evaluation of these cytokines was prioritized in our study, since TNF-α is an evident cytokine in an inflammation process, while IFN-γ activity has already been associated with microcephaly in studies with neuronal cells and patients serum." (PMID 32983175, 2020). "The risk of microcephaly was increased in newborns with hyperEPO+ISSI (ISSI defined by CRP, SAA, MPO, IL-6, TNF-α, TNF-R2, IL-8, MCP-1, ICAM-1, E-SEL, red), often more prominently than for ISSI alone." (PMID 25793991, 2015). "The investigators further found that a SNP in the tumor necrosis factor alpha (TNF-α) gene conferred a heightened risk of microcephaly compared to those babies lacking this SNP." (PMID 35844234, 2022). "In fatal cases of ZIKV-induced microcephaly, FAS, FASL, and tumour necrosis factor (TNF)-α were also overexpressed and directly regulated the mechanisms of neural parenchymal cell injury." (PMID 35746675, 2022). "The haplotypes of TNF also showed a different frequency between children with CZS and moderate or severe microcephaly, but in this scenario, a higher frequency of the TCG haplotype was found in children with a moderate microcephaly." (PMID 33672623, 2021). "Conversely, ZIKV-exposed participants without microcephaly displayed a general trend to decrease concentrations of inflammation mediators as IL-2, IL-4, IL-12p40, IL-12p70, TNF-α, TNF-β, IFN-γ, and the growth factors GCSF and EGF." (PMID 33875756, 2021). "In ZIKV-exposed neonates without microcephaly, GMCSF is the top node, also with only positive interactions, followed by pro-inflammatory cytokines such as IL-1RA, IL-12p70, IL-17A, TNF-α and IFN-α." (PMID 33875756, 2021).
ovarian dysfunction (12 papers, 2019 to 2025). The inability of the ovaries to function. "IFN‐γ and TNF‐α directly lead to granulosa cell dysfunction and contribute to follicle atresia and ovarian insufficiency." (PMID 37223018, 2023). "In POI and POF, inflammatory cytokines such as tumor necrosis factor-ɑ (TNF-a) and interleukin (IL) – 6 lead to apoptosis of ovarian granulosa cells and ovarian dysfunction." (PMID 35531876, 2022). "Taken together, these data indicate that IFN‐γ and TNF‐α directly result in granulosa cell dysfunction and thus contribute to follicle atresia and ovarian insufficiency." (PMID 34185428, 2021). "Compared to IL-6 and TNF-α, which primarily mediate systemic inflammation, VEGF is more directly involved in ovarian dysfunction and vascular abnormalities in PCOS." (PMID 40385768, 2025). "Moreover, we further investigated the paracrine ability of hAECs stimulated by TNF-α and INF-γ in vitro and evaluated the therapeutic effect of activated hAECs in a chemotherapy-induced ovarian dysfunction mouse model." (PMID 37993924, 2023). "Prestimulation with the proinflammatory factors TNF-α and IFN-γ could enhance the therapeutic efficacy of hAECs against chemotherapy-induced ovarian dysfunction, which may become a new feasible strategy to improve the therapeutic potential of hAECs in regenerative medicine." (PMID 37993924, 2023). "Therefore, the aim of the present study was to explore the modulatory effects of CAR or thymol on radiation-induced POF in vivo as well as the possible underlying mechanisms, particularly the impact on the cross-talk between TNF-α and IGF-1 signaling in irradiation-induced ovarian failure." (PMID 31531182, 2019).
plague (12 papers, 2007 to 2024). Plague is a severe bacterial infection caused by the gram-negative bacterium Yersinia pestis. "The Th1 immune response, in which cytokines like IFN-γ, TNF-α, and IL-2 play important roles, is necessary for plague prevention." (PMID 33014895, 2020). "Compared to MOD group, we found that ST could effectively decrease the body weight, triglyceride, total cholesterol, IL-6, TNF-α, plague area, numbers of heart lymphatic vessels, and T cells in lymph nodes through p38/JNK/ERK5." (PMID 32765273, 2020). "Our study further suggests cytokine-producing CD8 T cells may be a valuable addition to subunit plague vaccines and assays detecting Ag-specific TNFα production may be a particularly useful correlate of plague vaccine efficacy." (PMID 24854422, 2014). "V-mediated IL-10 secretion is thought to be involved in plague pathogenicity by preventing the release, to serum, of proinflammatory cytokines, such as TNF-α and IFN-γ, postinfection, and by subsequently suppressing the innate immune responses to plague infection." (PMID 17640293, 2007). "Notably, compared to the EV76-immunized group, EV76Δyp2-immunized mice exhibited a significantly higher secretion level of Th1-related cytokines, including TNF-α, IL-2, and IL-12p70, which have been recognized as crucial factors in conferring protection against plague." (PMID 38547321, 2024). "Moreover, it is thought that antibodies and cellular responses both contribute to protection against plague independently; it was shown that cytokine responses (i.e., TNF-α and IFN-γ) conferred significant protection, even in the absence of a protective antibody." (PMID 33669472, 2021). "LcrV triggers the release of IL-10 by host immune cells and suppresses proinflammatory cytokines such as TNF-α and INF-γ as well as innate defense mechanisms required to combat the pathogenesis of plague." (PMID 19701461, 2009). "Therefore, absence of TNF-α and IFN-γ in sera may be the major reason we observed poor protection efficacy against pneumonic plague." (PMID 19701461, 2009).
promyelocytic leukemia (12 papers, 2013 to 2024). "Recently, it was reported that Rh2 treatment induces apoptosis in human promyelocytic leukemia HL-60 cells via up-regulation of tumor necrosis factor-alpha (TNFα)." (PMID 35593465, 2022). "To investigate the interaction between cellular differentiation and TNF-α, we performed RNA-sequencing on two forms of the human HL-60/S4 promyelocytic leukemia cell line treated with TNF-α." (PMID 31263060, 2019). "The characteristic hemorrhages of acute promyelocytic leukemia (APL) are caused in part by the high expression of tissue factor (TF) on leukemic cells, which also produce TNF and IL-1β, proinflammatory cytokines known to increase TF in various cell types." (PMID 28343272, 2017). "The human promyelocytic leukemia cell line HL-60 was differentiated along the macrophage/monocyte lineage, and LPS stimulation with either 0.1 μg/mL or 1 μg/mL LPS led to dose-dependent TNFα and IL-6 induction." (PMID 33233817, 2020). "The A-vitamin derivate all-trans retinoic acid (ATRA), used in the treatment of acute promyelocytic leukemia (APL), has previously been shown to upregulate M-Sec at the mRNA level alone and in combination with tumor necrosis factor α (TNFα)." (PMID 27974700, 2017).